SYNE2 (spectrin repeat containing nuclear envelope protein 2)
Description:
Multi-isomeric modular protein which forms a linking network between organelles and the actin cytoskeleton to maintain the subcellular spatial organization. As a component of the LINC (LInker of Nucleoskeleton and Cytoskeleton) complex involved in the connection between the nuclear lamina and the cytoskeleton. The nucleocytoplasmic interactions established by the LINC complex play an important role in the transmission of mechanical forces across the nuclear envelope and in nuclear movement and positioning. Specifically, SYNE2 and SUN2 assemble in arrays of transmembrane actin-associated nuclear (TAN) lines which are bound to F-actin cables and couple the nucleus to retrograde actin flow during actin-dependent nuclear movement. May be involved in nucleus-centrosome attachment. During interkinetic nuclear migration (INM) at G2 phase and nuclear migration in neural progenitors its LINC complex association with SUN1/2 and probable association with cytoplasmic dynein-dynactin motor complexes functions to pull the nucleus toward the centrosome; SYNE1 and SYNE2 may act redundantly. During INM at G1 phase mediates respective LINC complex association with kinesin to push the nucleus away from the centrosome. Involved in nuclear migration in retinal photoreceptor progenitors. Required for centrosome migration to the apical cell surface during early ciliogenesis. Facilitates the relaxation of mechanical stress imposed by compressive actin fibers at the rupture site through its nteraction with SYN2.
Synonyms: KASH2; Syne-2; KIAA1011; NUA; DKFZP434H2235; Nesprin-2; NUANCE; Nesp2; EDMD5; TROPH
Tractability: Small molecule: a structure with a bound ligand is known. Antibody: UniProt places it where antibodies can reach, with high confidence; UniProt predicts a signal peptide or a membrane-spanning region; its Gene Ontology location is reachable by antibodies, with medium confidence. PROTAC: UniProt records ubiquitination sites on it; ubiquitination databases record sites on it; its protein half-life has been measured.
Gene: Protein-coding gene on chromosome 14 (63,761,899 to 64,226,433, forward strand). Ensembl gene ENSG00000054654.
Subcellular location: Nucleus outer membrane; Sarcoplasmic reticulum membrane; Cell membrane; Cytoplasm, cytoskeleton; Mitochondrion; Nucleus, nucleoplasm; Cytoplasm, myofibril, sarcomere, Z line; Cell junction, focal adhesion (Isoform 8)
Subcellular location (Human Protein Atlas): Intermediate filaments; Nuclear membrane; Primary cilium
Pathways (Reactome):
Reproduction: Meiotic synapsis
Gene Ontology:
Molecular function: cytoskeleton-nuclear membrane anchor activity; protein binding; actin binding
Biological process: centrosome localization; nuclear migration; nuclear migration along microfilament; positive regulation of cell migration; regulation of cilium assembly
Cellular component: cytoplasm; extracellular exosome; filopodium membrane; focal adhesion; intermediate filament cytoskeleton; lamellipodium membrane; meiotic nuclear membrane microtubule tethering complex; mitochondrion; nuclear envelope; nuclear lumen; nucleus; sarcoplasmic reticulum; Z disc; nuclear membrane; sarcomere; cytoskeleton; membrane; nuclear outer membrane; nucleoplasm; plasma membrane; sarcoplasmic reticulum membrane
Genetic constraint (gnomAD): Loss-of-function variants: 385 observed, 811.9 expected, observed/expected ratio (o/e) 0.47, 90% interval 0.44 to 0.52. The upper end of that interval is the gene's LOEUF score, 0.52, which puts it in group 2 of 6, group 1 being the genes least tolerant of losing a copy. Missense variants: 7,637 observed, 7,927.8 expected, observed/expected ratio (o/e) 0.96, 90% interval 0.94 to 0.98. Synonymous variants: 2,767 observed, 2,875.5 expected, observed/expected ratio (o/e) 0.96, 90% interval 0.93 to 0.99.
Homologues: Orthologues: chimpanzee SYNE2 (99% identical), macaque SYNE2 (96% identical), pig SYNE2 (81% identical), dog SYNE2 (80% identical), guinea pig SYNE2 (75% identical), rat Syne2 (71% identical), mouse Syne2 (70% identical), tropical clawed frog syne4 (4% identical), zebrafish syne2b (0% identical). Paralogues in human: SYNE1 (30% identical), DST (13% identical), MACF1 (13% identical), PLEC (8% identical), SPTBN1 (8% identical), SPTB (8% identical), SPTBN2 (8% identical), SPTBN4 (7% identical), SPTBN5 (7% identical), DMD (7% identical), UTRN (7% identical), PKHD1L1 (5% identical), and 24 more.